IL18 (interleukin 18)
Diseases named in the same sentence as IL18 in open-access papers (continued):
Sharing a sentence is not in itself a finding about the gene and the disease.
lung carcinoma (52 papers, 2013 to 2025). "In contrast, increased genetic predisposition to higher interleukin-18 (IL-18) and interferon gamma-induced protein 10 (IP-10) levels are negatively associated with lung cancer risk." (PMID 38957317, 2024). "We identified four inflammatory mediators - SCF, IL-1β, IL-18, and IP-10 - involved in genetic susceptibility to lung cancer overall and in specific histologic subtypes, as well as differences based on smoking status." (PMID 38957317, 2024). "In contrast, increased genetic predisposition to higher levels of interleukin-18 (IL-18) and interferon gamma-induced protein 10 (IP-10) is negatively associated with lung cancer risk." (PMID 38957317, 2024). "The current research aims to clarify the relationship of IL-18 gene polymorphism with lung cancer susceptibility through experimental investigation and meta-analysis, providing insights for lung cancer prevention and treatment." (PMID 39006070, 2024). "We identify genetically predicted IL-18 levels as being associated with an increased risk of lung cancer." (PMID 38527997, 2024). "These included higher levels of IL-18 with reduced risk of lung cancer (Probable, ORSD = 0.89, 95% CI: 0.83–0.96, P = 2.00 × 10−3), with specificity for lung cancer in never smokers." (PMID 38527997, 2024). "In contrast, IL-18 was inversely associated with lung cancer, while IL-13 showed a direct correlation." (PMID 39267832, 2024). "The IL-18 -607 C/A polymorphism appears to significantly increase the risk of lung cancer in the population of Eastern China." (PMID 39006070, 2024). "Only the association of IL-18 in relation to lung cancer was replicated (p < 0.05) in the UK Biobank; power though was substantially limited (5%) in all analyses." (PMID 35012533, 2022). "Our analysis also showed an inverse association between genetically proxied IL-18 concentrations and overall lung cancer and lung adenocarcinoma." (PMID 35012533, 2022). "To explore the role of NLRP3 inflammasome responses in lung cancer with Qi-yin deficiency, we first detected the serum levels of IL-1β and IL-18." (PMID 35292015, 2022). "IL-18 is reported to be a candidate causal marker for lung cancer, as it confers a lower risk of developing lung cancer." (PMID 34475499, 2021). "This MR study found preliminary evidence that genetically predicted levels of four inflammatory cytokines—SCF, IL-1β, IL-18, and IP-10—may causally influence lung cancer risk overall, in specific histologic subtypes, and stratified by smoking status." (PMID 38957317, 2024). "This MR study found preliminary evidence that genetically predicted levels of four inflammatory cytokines—SCF, IL-1β, IL-18, and IP-10—may causally influence lung cancer risk in an overall and subtype-specific manner, as well as stratified by smoking status." (PMID 38957317, 2024). "Notably, our analysis revealed novel causal links between SCF, IL-1β, IL-18, and IP-10 in overall lung cancer as well as specific histological subtypes, highlighting important etiological roles for these cytokines." (PMID 38957317, 2024). "In this study, we found that BFXJY could inhibit the tumor growth in lung cancer with Qi-yin deficiency by reducing the production of IL-1β and IL-18 and inhibiting NLRP3 inflammasome activation, which might be associated with the inhibition of PKC signaling." (PMID 35292015, 2022). "In lung cancer, studies have shown upregulation of inflammasome components like IL-1β and IL-18 in the serum of lung cancer patients as compared with adjacent lung tissues." (PMID 41376623, 2025). "Our IVW analysis results showed that IL-18 levels provide the following outcome for lung cancer (p = 2.72E-03; OR 95% CI = 0.76 (0.64, 0.91))." (PMID 39267832, 2024). "Overall, the effects of IL-18 in lung cancer are complex and involve immune response promotion, tumor growth inhibition, and inflammatory response and angiogenesis promotion, which eventually affect tumor development." (PMID 39267832, 2024).
lung carcinoma (continued). "In summary, our study identified two axes in the immune cell-inflammatory factor-lung cancer pathway, namely HLA DR on CD33dim HLA DR+ CD11b+ - Interleukin-18 - lung cancer and HLA DR on CD33dim HLA DR+ CD11b+ - Interleukin-13 - lung cancer." (PMID 39267832, 2024). "Studies have revealed that IL-18 can be consistently and effectively expressed in A549 human lung cancer cells, leading to the inhibition of cell proliferation and tumor cell growth, as well as the promotion of tumor cell apoptosis." (PMID 39267832, 2024). "1L-1β and IL-18 are of particular interest in lung cancer because they promote the initiation, progression, and metastasis of the disease." (PMID 37715239, 2023). "IL-1 β and IL-18 are of particular interest in lung cancer because they promote the initiation, progression, and metastasis of the disease." (PMID 37715239, 2023). "In this study, we show that long‐term exposure of lung cancer cells to PM2.5 can activate AhR to promote the expression of TMPRSS2 and IL18 and promote lung cancer progression." (PMID 36975376, 2023). "The results demonstrated that treatment of lung cancer A549 cells with LPS and ATP induced the expression of IL-6 and inflammasome-related cytokines IL-1β and IL-18, as well as increased NLRP3 gene expression." (PMID 38026959, 2023). "To evaluate the role of TMPRSS2 expression in lung cancer progression in vivo, we examined the expression levels of TMPRSS2, IL18, and nuclear AhR by IHC in tumor specimens from 25 lung cancer patients." (PMID 36975376, 2023). "AhR nuclear expression also correlated with TMPRSS2 and IL18 expression and cancer stage in human lung cancer tissue." (PMID 37696458, 2023). "Three SNPs: rs1799732, rs5744256, and rs2306022 from DRD2, IL-18, and ITGA11 were among the five SNPs that MDR selected as best associated with lung cancer." (PMID 38137497, 2023). "We further observed an MDM subset expressing inflammation and phagocytosis-associated genes (cluster 4; CCL18, IL18, C1QA and TREM2) and enriched for samples from patients with COVID-19 pneumonia, as well as samples from patients with lung carcinoma." (PMID 37291214, 2023). "Clinical correlation of TMPRSS2 expression with age, sex, nuclear AhR, IL18, and overall stage in 25 lung cancer patientsa." (PMID 36975376, 2023). "Our observations are in line with findings from experimental research that has demonstrated an antitumour activity of IL-18 on lung cancer." (PMID 35012533, 2022). "In lung cancer, IL-18 contributes to the expansion of CD8+ Tbet+ TILs that express IL-18 receptors and produce IFNγ within the tumor microenvironment." (PMID 33430344, 2021). "We primarily assessed the effects of genetically predicted IL-1α, IL-1β, IL-1Ra, IL-1Racp, IL-18, and IL-18BP with lung cancer and its subtypes of LUAD and LUSC, because LUAD is more common than LUSC in people of European ancestry." (PMID 34475499, 2021). "Previous studies also demonstrated that NLRP3 inflammasome, and its complex (IL-11β and IL-18) promote tumor growth, proliferation, invasion and metastasis in lung cancer, melanoma, breast cancer and HNSCC." (PMID 31312615, 2019). "The proinflammatory cytokine IL-18 confers protective effects against cancer proliferation, such as that of lung cancer, in several murine models, and the benefits of recombinant human IL-18 have been shown in preclinical trials for cancer treatment." (PMID 30925760, 2019). "NLRP3 inflammasome components IL-1β and IL-18 were found to be highly expressed in lung cancer cell lines and tissues than in cancer-adjacent normal tissues." (PMID 28865486, 2017). "Over-expression of IL-18 was found among cancer patients with malignant prognosis, including oral cancer, lung cancer, gastric cancer, pancreatic cancer, and hepatocellular carcinoma." (PMID 24349532, 2013).
lung carcinoma (continued). "A recent study indicated that TREM2 macrophages not only secreted IL-18 BP to inhibit the impact of IL-18 on NK cells but also alleviated the DC-derived IL-15, which drives NK cell dysfunction in lung cancer and provides a deeper insight into dual targeting of NK cells and TAMs." (PMID 40380196, 2025). "In addition, TREM2+ macrophages diminish the recruitment and cytolytic activity of NK cells by disabling IL-18 signaling in lung cancer." (PMID 39838454, 2025). "In a recent comprehensive study, we expanded upon previous single-item MR findings that linked CCL27/CTACK positively with lung cancer incidence in non-smokers, and IL-18 negatively with lung cancer and lung adenocarcinoma rates." (PMID 39132165, 2024). "Additionally, IL-18 levels were negatively correlated with lung cancer, whereas IL-13 levels were positively correlated with lung cancer." (PMID 39267832, 2024). "Additionally, research indicates that IL-18 plays a crucial role in enhancing immune responses and positively influencing immunotherapy for lung cancer by modulating the expansion and phenotypic changes of NK cells." (PMID 39267832, 2024). "In addition, IL-13 and IL-18 play an important role in the relationship between HLA DR expression on CD33dim HLA DR+ CD11b+ cells and lung cancer, and IL-18 plays an important role in lung cancer." (PMID 39267832, 2024). "Genetically predicted levels of the chemokine interleukin-18 (IL-18) (OR = 0.942, 95% CI: 0.897–0.990, P = 0.018) exerted significant negative causal effects on overall lung cancer risk in this analysis." (PMID 38957317, 2024). "In agreement, previous reports have indicated that ATP stimulation of alveolar macrophages, derived from both IPF and lung cancer patients, led exclusively to an elevation in IL-18 levels, which was explained by an impaired NLRP3 inflammasome and a defective autophagy in IPF patients." (PMID 38300690, 2024). "In the context of lung cancer, IL-18 serves diverse functions." (PMID 39267832, 2024). "However, the change in IL-18 levels was very modest in lung epithelium compared with lung cancer cells, indicating a more profound role of IL-1β in lung epithelium-induced inflammation." (PMID 36694200, 2023). "For example, it has been reported that only sustained circuit of IL-18 in lung cancer, rather than contemporary exposure, can potentially cause anti-tumor immunosurveillance and further inhibit tumor growth and metastasis." (PMID 35655081, 2022). "In addition, the levels of NLRP3, cleaved caspase-1, IL-1β and IL-18 were increased in the two lung cancer cells with miR-223-3p inhibition, and the corresponding results were contrary in miR-223-3p mimic group." (PMID 36276078, 2022). "Besides, the levels of NLRP3, cleaved caspase-1, IL-1β and IL-18 were increased in the two lung cancer cells." (PMID 36276078, 2022). "Besides being produced by immune cells including antigen presenting cells, IL-18 is expressed by epithelial cells and by cancer cells of some solid tumors such as melanoma, lung cancer, prostate, and colon cancer." (PMID 33430344, 2021). "Importantly, IL-18 production is one of the few cytokines lost rapidly during progression of lung cancer in patients as identified by deep immunophenotyping recently." (PMID 33255437, 2020). "The role of high IL-18 secretion by lung cancer AMs and PBMCs as observed here, in carcinogenesis remains unclear, since it exerts both antitumor and protumor effects." (PMID 30365491, 2018). "Specifically, IVW analysis revealed interleukin-18 (IL-18) exerted significant negative causal effects on lung cancer risk (OR = 0.942, 95% CI: 0.897–0.990, P = 0.018), while eotaxin had significant positive causal effects (OR = 1.061, 95% CI: 1.002–1.123, P = 0.043)." (PMID 38957317, 2024).
lung carcinoma (continued). "The activation of NLRP3 inflammasome could promote the proliferation and migration of lung adenocarcinoma A549 cells by mediating the release of IL-18 and IL-1β through the caspase-1 dependent pyroptosis pathway, while blocking IL-18 and IL-1β signaling could inhibit the progression of lung cancer." (PMID 37194012, 2023). "Additionally, it has been suggested that IL18 may promote lung cancer cell proliferation and contribute to lung cancer progression." (PMID 37524704, 2023). "Our analysis identified six key immune regulatory genes (TLR2, TLR4, CCR7, IL18, TIRAP and FOXP3) that show differential expression between lung cancer and normal tissues and demonstrate potential prognostic value." (PMID 41319095, 2025). "Six key immune genes (TLR2, TLR4, CCR7, IL18, TIRAP and FOXP3) showed cell‐type specific expression patterns in the lung cancer microenvironment." (PMID 41319095, 2025). "Although we showed that HEI3090 enhances IL-18 release in vivo, it is of interest to study its impact on P2RX7 activation in vivo, especially since HEI3090 is a promising molecule for treatment of lung cancer." (PMID 36600200, 2023). "Moreover, in lung cancer, previous studies have shown that NLRP3 can enhance the proliferation of A549 cells through IL-1β/ERK/CREB and IL-18/AKT/CREK signaling pathways, and promote tumor metastasis by reducing E-cadherin and increasing Snail expression." (PMID 36349316, 2022). "Plasma cytokines IL-18 and CXCL10 could indicate the anti-PD-1/PD-L1 treatment response in lung cancer patients and play an important role in selecting patients benefiting from PD-1/PD-L1 inhibitors." (PMID 35468838, 2022). "Specifically, the expression of CD16-CD56 on NK T cells and HLA DR on CD33dim HLA DR+ CD11b+ cells exhibited a negative correlation with lung cancer, whereas the expression of HLA DR on CD33dim HLA DR+ CD11b+ cells was positively correlated with IL-18 and IL-13 levels." (PMID 39267832, 2024). "Furthermore, we examined whether IL1β and IL18, which are the downstream mediators of the NLRP3 inflammasome, can promote the proliferation of lung cancer cells." (PMID 37524704, 2023). "In addition, we were not able to detect any increase in other inflammatory cytokines (e.g., IL-1α, IL-1β, IFN-α, IL-8 and IL-18) from both healthy and lung cancer-derived PBMCs after S1P stimulation (data not shown)." (PMID 36010601, 2022). "Then, the migration and invasion of lung cancer cells were detected with miR-223-3p mimic and inhibitor using Transwell assay, at the same time the expression of NLRP3, cleaved caspase-1, IL-1β and IL-18 was determined using Western Blot and immunohistochemistry assay." (PMID 36276078, 2022). "NLRP3 inflammasome activation-induced IL-1β and IL-18 in lung cancer may work through mechanisms other than the caspase-1 pathway, indicating that NLRP3 inflammasome can mediate the release of IL-1β and IL-18 through caspase-1-dependent or -independent pathways." (PMID 33613533, 2020).
pancreatic cancer (52 papers, 2008 to 2026). "Interleukin-18 (IL-18) is a pro-inflammatory cytokine, and higher IL-18 expression in pancreatic tumors is associated with poor prognosis." (PMID 41940532, 2026). "A lower number of studies focusing on tissue expression of IL-18 have also shown that higher IL18 in pancreatic cancer tissues is associated with shorter OSs and increased invasion and metastasis." (PMID 38785507, 2024). "A previous study found that IL-18 played a key role in the pathogenesis of both CD and pancreatic cancer through a common pathogenic pathway, affecting the immune response and tumor microenvironment by activating immune cells." (PMID 38404590, 2024). "In pancreatic cancer, elevated serum IL-6 and IL-10 concentrations have been linked with worse prognosis, as has the pro-inflammatory cytokine IL-18." (PMID 35034144, 2022). "Although 5-fluorouracil (5-FU) has been reported to induce the release of bioactive (mature/cleaved) IL-18 from the pancreatic cancer cell line Capan-2, the underlying mechanism remains unclear." (PMID 41940532, 2026). "Finally, our analysis of inflammatory biomarkers shows that AIF-1, IL-12A and IL-18 are directly related to pancreatic cancer mortality, whereas IL-10 shows an inverse association." (PMID 38785507, 2024). "Studies have indicated that eosinophils and pancreatic cancer may be associated with inflammatory response, IL-5, IL-18, and degranulation, even if the precise mechanism behind this association is still unclear." (PMID 39465831, 2024). "Furthermore, IL-18 is overexpressed in certain tumors and is associated with poor prognosis, as observed in pancreatic cancer, renal cell carcinoma, and extranodal natural killer/T-cell lymphoma." (PMID 38066523, 2023). "Furthermore, IL-1β can enhance the invasive capacity of pancreatic cancer cells, while free IL-18 levels are increased in the blood of pancreatic cancer patients and are associated with poor survival." (PMID 32974137, 2020). "Its ability to inhibit IL-18/NLRP3-regulated NICD suggests potential for microvascular-targeted pancreatic cancer treatment strategies." (PMID 40422787, 2025). "The combination of IL-18 blocking agent (IL-18 BP) with the hypoxic BXPC-3 conditioned medium (CM) confirmed that 8 inhibits pancreatic cancer angiogenesis by suppressing IL-18 release." (PMID 40422787, 2025). "Specifically, pancreatic cancer cells promote the proliferation of Bregs through the secretion of IL-18, and, in turn, Bregs aid in immune evasion and tumor growth by expressing PD-L1 and IL-35." (PMID 39682280, 2024). "Despite fewer studies, previous works have also found that pancreatic carcinoma cells not only produce IL-18, but also IL-12, and that higher serum and tissue levels of IL-12 can be found in pancreatic cancer cells." (PMID 38785507, 2024). "In pancreatic cancer, IL-18 promotes tumor progression and metastasis through the NF-κB signaling pathway, with increased NF-κB perpetuating elevated IL-18 expression and forming a positive feedback loop." (PMID 38066523, 2023). "Up-regulation of PIN1 in pancreatic cancer has been reported to activate NF-κB -IL-18 and stimulate the proliferation and invasion of cancer cells." (PMID 37105032, 2023). "As a result, five highly expressed PRGs, including apoptotic-related genes (BAK1 and TP63), CHMP4C, IL18, and NLRP2, were categorized as high risk in this prognostic model and provided poor prognoses for pancreatic cancer." (PMID 37893166, 2023). "Not only levels of IL-18 were increased in tumor tissue of mouse models of pancreatic cancers, it was also shown to have a pro-tumoral activity." (PMID 37298187, 2023). "An earlier study had shown that NF-κB-dependent expression of IL-18 by human and murine pancreatic tumor cells increased their proliferation and invasion in vitro and in vivo, and they were blocked in the presence of IL-18BP." (PMID 37298187, 2023).